FGF9 (fibroblast growth factor 9)
Diseases named in the same sentence as FGF9 in open-access papers (continued):
Sharing a sentence is not in itself a finding about the gene and the disease.
idiopathic pulmonary fibrosis (11 papers, 2014 to 2025). Idiopathic pulmonary fibrosis (IPF) is a nonneoplastic pulmonary disease that is characterized by the formation of scar tissue within the lungs in the absence of any known cause. "Genetic deficiency of FGF-9 had been observed in several pathological conditions, including abnormal bone repairment, idiopathic pulmonary fibrosis, myocardial infarction, and tumorigenesis." (PMID 38173028, 2024). "FGF-9 has also recently been linked to human lung fibrosis but its role in this disease has to date not been experimentally defined." (PMID 24904415, 2014). "We did note an unexpected increase in FGF-9, a neuroimmune molecule with manifold effects on embryonic development that may be implicated in human lung fibrosis." (PMID 24904415, 2014). "In conclusion, our study demonstrates that UC-MSC-derived exosomal miR-486-5p regulates fibroblast differentiation by targeting FGF9, ultimately preventing the progression of pulmonary fibrosis." (PMID 40692863, 2025). "In contrast, FGF9 is elevated in tissue samples from patients with mild to severe idiopathic pulmonary fibrosis (IPF), and FGF9 and FGF18 both contribute to the development of IPF in tissue culture." (PMID 35675358, 2022). "Tregs suppressed TGF-β-induced pulmonary fibrosis through decreasing fibroblast growth factor 9 (FGF-9) expression by parenchymal cells and alveolar macrophages." (PMID 32708044, 2020). "In contrast, FGF9-positive cells bearing the morphology of alveolar epithelial cells markedly increased in the setting of BLM-induced pulmonary fibrosis, whereas FGF9-positive cells decreased following the adoptive transfer of Tregs." (PMID 29690905, 2018). "Next, we validated the role of FGF9 in the progression of pulmonary fibrosis." (PMID 40692863, 2025). "FGF9 is a neuroimmune system molecule with manifold effects on embryonic development and mesenchymal proliferation that may be involved in human lung fibrosis." (PMID 29690905, 2018). "We next sought to assess whether FGF-9 promotes TGF-β1 induced lung fibrosis in our model." (PMID 24904415, 2014). "The fibroblast growth factor 9 (FGF9) and 18 (FGF18) also inhibit myofibroblast differentiation in idiopathic pulmonary fibrosis and their biological effects are partially driven by FGFR344." (PMID 28717200, 2017). "While increased detection of FGF-9 has been reported in lungs of patients with IPF a role for FGF-9 in the regulation of experimentally induced lung fibrosis has yet to be described." (PMID 24904415, 2014). "While in vivo data demonstrated that antibody-mediated Treg depletion augmented FGF9 expression in mice overexpressing TGF-β1, the effect of adoptively transferred Tregs on FGF9 expression in BLM-induced lung fibrosis is not yet described." (PMID 29690905, 2018). "While FGF-9 has been shown to be expressed in fibrotic human lung and human fibroblasts in response to TGF-β1 the studies presented here provide a putative mechanistic role for this molecule in pulmonary fibrosis via the accumulation of fibrocytes within the TGF-β1 exposed lung." (PMID 24904415, 2014).
lung carcinoma (11 papers, 2016 to 2025). "Additionally, expression of FGF9 in lung cancer was associated with poorer prognosis." (PMID 27056048, 2016). "This was also observed in FGF2- and FGF9-high expressing patients with bronchus and lung cancer." (PMID 37880373, 2023). "High expression of FGF9 in lung cancer was identified as a novel unfavourable prognostic indicator." (PMID 27166269, 2016). "But the FGF9 serum concentration in lung cancer patients was too low to be detected by ELISA assay." (PMID 27166269, 2016). "In addition, downregulation of FGF9 was reported to regulate tumorigenesis in lungs cancer." (PMID 34061869, 2021). "For instance, FGF9 activates FAK, AKT and ERK signalling pathways to induce EMT, thereby promoting lung cancer tumorigenesis and liver metastasis." (PMID 40977522, 2025). "In this study, miR-4317 targets fibroblast growth factor 9 (FGF9) and cyclin D2 (CCND2), affecting the migration and invasion of lung cancer cells." (PMID 39408656, 2024). "Studies have indicated that FGF9 activates FAK, AKT and ERK signalling through FGFR1, inducing EMT to stimulate tumourigenesis and hepatic metastasis in Lewis lung carcinoma cells." (PMID 39001509, 2024). "FGF2, FGF9 and FGF10 can stimulate proliferation, treatment sensitivity, and apoptosis of lung cancer cells." (PMID 27166269, 2016). "Furthermore, when we screened 135 lung cancer and 1,182 other cancer cell lines, numerous cells that expressed high FGF2 or FGF9 showed relatively higher expression levels of FGFR1, FGFR2, or both." (PMID 37880373, 2023).
melanoma (11 papers, 2007 to 2023). A malignant, usually aggressive tumor composed of atypical, neoplastic melanocytes. "Given the putative germ line association of FGF9 with melanoma risk in humans, our finding in dog osteosarcoma presents a valuable model in which to dissect and target the molecular mechanisms." (PMID 30890123, 2019). "For example, propofol can inhibit the proliferation of mammary cancer MCF-7 cells by downregulating the expression of miR-21 and can also inhibit the activity of melanoma cells by adjusting miR-137 and FGF9." (PMID 34956562, 2021). "On the other hand, the top downregulated genes formed 4 subgroups and were related to melanogenesis (Wnt5a, Mitf, Pomc, Mc1r, Kit), melanoma (Fgf9, Fgf12, Fgf2), MAPK signaling pathway (Ncam1, Prkcb, Map3k4, Pla2g4a, Mapk14, Mapk11), and aging (Tgfbr1, Il6, Nox4)." (PMID 36555664, 2022). "FGF9 was recently shown to have borderline genome wide significance in a melanoma GWAS." (PMID 30890123, 2019). "Indeed, Prahallad and co-workers revealed that SHP-2 knockout clones of SK-Mel888 BRAF(V600E) mutant melanoma cells were unable to confer Vemurafenib resistance, following HGF, fibroblast growth factor 9 (FGF9), and stem cell factor (SCF) exposure." (PMID 33003469, 2020).
breast carcinoma (10 papers, 2007 to 2023). "FGF9 is capable of inducing cancer stem-like cell properties in breast cancer cell lines and freshly isolated breast cancer cells through FGFR activation." (PMID 35193394, 2022). "miR-187-3p increases gemcitabine sensitivity in breast cancer cells by downregulating FGF9 expression." (PMID 34895047, 2021). "Lidocaine inhibited proliferation, migration, and invasion of BC cell line MCF-7 by modulating the MicroRNA-495-3p/Fibroblast Growth Factor 9 axis.The overexpression of FGF9 inhibited the inhibitory effect of lidocaine on the proliferation, migration, and invasion of breast cancer MCF-7 cells." (PMID 35163815, 2022). "On the contrary, FGF9 is highly expressed in breast cancer compared with normal tissue, although its expression is not as high as the expression of other FGFs like FGF1." (PMID 35193394, 2022). "The role of FGF-9 in breast cancer has not been well established, although one study found that estrogen could expand the breast CSC population through a paracrine mechanism that involved FGF9." (PMID 26361584, 2015).
depression (9 papers, 2017 to 2025). "Carnosic acid has a tendency to reduce FGF9 expression in post-stroke depression rats, while also reversing the relationship between FGF9 and FGFR-3, and reducing infarct volume in PSD rats." (PMID 40458804, 2025). "This was supported by studies showing that FGF9 expression was significantly up-regulated in frontal cortex and locus coeruleus of patients with major depression." (PMID 35546939, 2022). "Recently, researchers thought that the pathway of APN/fibroblast growth factor 9 had an important role in the development of depression." (PMID 35372107, 2022). "Exogenous FGF9 administration was found to increase depression-like behaviors, and exogenous FGF9 knockdown in the dentate gyrus improved anxiety-like behavior in rats." (PMID 32184729, 2020). "It is well to be reminded that, FGF2 and FGF9 were found to have the opposite effect through chronic administration of FGFs, that is, FGF2 reduced anxiety- and depression-like behaviors, while FGF9 increased anxiety- and depression-like behaviors." (PMID 30804785, 2019). "Currently, among the twenty-two identified FGFs, FGF2, FGF9, FGF21, and FGF22 have been found to be associated with depression." (PMID 30804785, 2019). "Further experiments found that administrating exogenous FGF9 increased anxiety- and depression-like behaviors, while knocking down endogenous FGF9 expression in the dentate gyrus by lentiviral vector showed decreased anxiety-like behavior in rats." (PMID 30804785, 2019). "Increased levels of FGF9 in the hippocampus of subjects with major depressive disorder have been observed." (PMID 28546539, 2017). "Administration of FGF9 to male rats increases anxiety and depression-like behavior, and FGF9 stimulates expression of SPRY4 in vitro." (PMID 29096718, 2017). "In addition to FGF2, FGF9 has been proposed as a novel modulator for mood disorder, as both preclinical and clinical data indicated a role of FGF9 in depression." (PMID 35546939, 2022). "In humans with major depression, we recently identified FGF9 as a gene of interest." (PMID 29096718, 2017). "Thus, these analyses confirmed the alteration of FGF9 in depressive disorders, and show also its up-regulation in the altered hippocampus of AD-affected mice." (PMID 28546539, 2017). "Here, we mainly concentrated on the reported depression-related FGF system members, including FGFR1, FGF2, FGF9, FGF21, and FGF22." (PMID 30804785, 2019).
myocardial infarction (8 papers, 2015 to 2025). Gross necrosis of the myocardium, as a result of interruption of the blood supply to the area, as in coronary thrombosis. "A previous study demonstrated that FGF9 attenuated myocardial infarction in diabetic mice by increasing the levels of anti-inflammatory cytokines and M2 macrophage differentiation, thereby reducing adverse remodeling and improving cardiac function." (PMID 40526701, 2025). "Exogenous FGF9 protein, or its specific expression in the heart under specific conditions, may improve function following myocardial infarction." (PMID 40526701, 2025). "However, it has been reported that FGF-9 enhanced M2 differentiation post-myocardial infarction accompanying with significantly elevated IL-10 secretion." (PMID 31852428, 2019). "In AAA, both the medial and adventitial layers of the vessel wall are significantly more vascularized compared with nonaneurysmal tissue, and it is therefore interesting to note that FGF9 has been shown to enhance angiogenesis and neovascularization within mouse models of myocardial infarction." (PMID 27899403, 2017). "FGF9 possesses novel therapeutic potential due to its ability to mediate monocyte to M2 macrophage differentiation and confer cardiac protection in the post-myocardial infarction diabetic heart." (PMID 27803896, 2016). "Db/db diabetic mice were assigned to sham, myocardial infarction (MI), and MI+FGF-9 groups." (PMID 25768089, 2015). "After myocardial infarction, transgenic FGF9 enhances hypertrophy in the noninfarcted left ventricular myocardium with increased microvessel density, reduces interstitial fibrosis, attenuates fetal gene expression, and improves systolic function and heart failure mortality." (PMID 27803896, 2016).
craniosynostosis (7 papers, 2015 to 2025). Craniosynostosis is defined as the premature fusion of one or more cranial sutures leading to secondary distortion of skull shape resulting in skull deformities with a variable presentation. "In the developing bone, missense mutations in the Fgf-9 gene lead to joint synostosis and craniosynostosis." (PMID 25742620, 2015). "Additionally, in humans, an FGF9 missense mutation led to craniosynostosis with multiple synostosis." (PMID 37325554, 2023). "Furthermore, patients carrying FGF9 variants may exhibit craniosynostosis (scaphocephaly, dolichocephaly) and cleft palate." (PMID 40673520, 2025). "We highlight two core genes (FGF9, PRRX1) in which variants may impact key aspects of cranial suture biology, but for the majority of the genes it is likely that craniosynostosis is a rare consequence of mutation." (PMID 36980886, 2023). "Muenke syndrome in humans, characterized by craniosynostosis with uni- or bicoronal synostosis, comes from an FGFR3 Pro250Arg mutation resulting in the increased binding affinity of FGFR3 to its ligand, such as FGF9, by the substitution of a bulkier residue." (PMID 37325554, 2023). "Distinguishing these possibilities could be important for functional interpretation: for example, in Alt2 and Alt3, a copy of the 244 kb segment is brought into closer proximity with FGF9, a known disease gene in craniosynostosis, whereas in Alt1, the rearrangement occurs remotely to this gene." (PMID 41233895, 2025).
Obesity (7 papers, 2019 to 2025). Accumulation of substantial excess body fat. "Recently two studies showed that FGF9 regulates browning of white adipocytes and is associated with human obesity." (PMID 35517790, 2022). "Interestingly, recently two studies showed that FGF9 regulates browning of white adipocytes and is associated with human obesity." (PMID 35517790, 2022). "To address the role of the FGF6/9-FGFR3 pathway in human thermogenic function and obesity, we measured the expression of FGF6, FGF9, and FGFR3 in human adipose tissue biopsies." (PMID 32184391, 2020). "FGF9 is a member of the fibroblast growth factor (FGF) family that mainly binds receptors FGFR2 and FGFR3 and plays a crucial role in regulating cell growth, embryonic development, skeletal development, energy metabolism, and obesity." (PMID 40867703, 2025). "Interestingly FGF9 mRNA expression was rather downregulated in a methionine and choline–deficient diet (MCDD) model, which is a well-known model of steatohepatitis without obesity and HCC development." (PMID 31862949, 2019). "In our study, the increased expression of FGF9 in PCOS participants was lost when stratified for BMI, indicating that it is reflective of obesity rather than inherent to PCOS." (PMID 40072105, 2025).
Anxiety (6 papers, 2017 to 2025). Intense feelings of nervousness, tension, or panic often arise in response to interpersonal stresses. "In rodent models of affective disorders, chronic social defeat stress increased anxiety, compromised social interaction, and decreased body weight, and was associated with increased hippocampal FGF9 expression." (PMID 28546539, 2017).
endometrial cancer (6 papers, 2012 to 2020). Primary or metastatic malignant neoplasm involving the endometrium (mucous membrane that lines the endometrial cavity). "More interestingly, the expression or mutation of FGF9 correlates with β-catenin in ovarian, colorectal and endometrial carcinomas." (PMID 32366371, 2020). "Sox7 was reportedly downregulated in endometrial cancer showing increased β-catenin, CyclinD1, and fibroblast growth factor 9 (FGF9)." (PMID 26871472, 2016). "To further investigate the expression status of Sox7 and Wnt/β-catenin activity, we evaluated the expressions of Sox7, β-catenin, CyclinD1 and FGF9 by immunohistochemical analysis on a human endometrial cancer array (EMC1501, Pantomics, Inc)." (PMID 23295859, 2012). "To investigate the suppression effects of Sox7 on Wnt/β-catenin activity of endometrial cancer, we particularly examined the expression levels of CyclinD1 and FGF9 in β-catenin highly expressing endometrial cancer samples which had either with or without expression of Sox7." (PMID 23295859, 2012). "Decreased FGF9 activity may be the result of increased miR-182 expression in G2 endometrial cancer." (PMID 31795319, 2019). "A previous study showed that SOX7 might be a negative regulator of Wnt/β-catenin signaling pathway through disrupting the transcriptional activity of β-catenin–TCF/LEF complex and its downstream targets, such as Cyclin D1, c-Myc, and FGF9 in endometrial cancer." (PMID 29029454, 2017). "Our finding showed that there was a reciprocal relationship between Sox7 and the levels of FGF9 and SFN which were 17.9-fold (P = 0.048) and 7.27-fold (P = 0.008), respectively, higher in endometrial cancer as compared with normal endometrium." (PMID 23295859, 2012).
cleft palate (5 papers, 2016 to 2025). Cleft palate is a fissure type embryopathy that affects the soft and hard palate to varying degrees. "Here, we report on a multigenerational family with a total of 29 affected individuals, who display some previously unknown features such as cleft palate and conductive hearing impairment, with a novel, likely pathogenic, heterozygous missense variant in FGF9." (PMID 36980996, 2023). "A non-syndromic case of cleft palate with the Fgf9 T > C mutation was detected in 2007." (PMID 36358989, 2022). "Moreover, cleft palate has been observed in Fgf9–/– mice with 40% penetrance, but the underlying mechanism has not been elaborated." (PMID 33959039, 2021). "In our pilot study, we generated a Fgf9−/− mouse model with 100% penetrance of cleft palate, delayed palatal elevation, and decreased hyaluronic acid accumulation." (PMID 36358989, 2022). "In addition, cleft palate has been noted in Fgf9−/− mice with 40% penetrance by different knock-out gene sites." (PMID 36358989, 2022). "To verify our hypothesis and explore Fgf9’s possible functions, we generate an Fgf9 knockout murine model with 100% penetrance of cleft palate." (PMID 33959039, 2021). "However, the syndrome of cleft palate, deficient mandibular size, premature partial ossification, and occipital deficiency in Fgf9 knockout mice generated in our study has not been reported in mice or humans." (PMID 33959039, 2021). "Prior to this report, a cleft palate has only been described once in a human with SYNS3; however, the authors of this study did not discuss the cleft palate in relation to the FGF9 pathogenic variant." (PMID 36980996, 2023).
colorectal cancer (5 papers, 2018 to 2023). A primary or metastatic malignant neoplasm that affects the colon or rectum. "Consistently, a recent study showed that FGF9 gene amplification was associated with resistance of colorectal cancer cells to cetuximab." (PMID 29774115, 2018). "In addition, Fgf9 stimulates the proliferation of vascular smooth muscle, epithelial, and colorectal cancer cells." (PMID 36120469, 2022). "Furthermore, the 37 colorectal carcinoma specimens were stratified as 22 high- and 15 low-FGF9-expressing tumors (FGF9 was classified as high expression if the immunostaining score was more than four, otherwise it was classified as low expression)." (PMID 32366371, 2020). "FGF8, FGF9, FGF10, FGF18, and FGF23 are involved in the progression of colorectal cancer, and FGF9 expression is negatively correlated with patients’ survival." (PMID 33649301, 2021).